MIR887 (microRNA 887)
Synonyms: hsa-mir-887; MIRN887
Gene: MicroRNA gene on chromosome 5 (15,935,182 to 15,935,260, forward strand). Ensembl gene ENSG00000216077.
Gene Ontology:
Biological process: miRNA-mediated post-transcriptional gene silencing
Cellular component: RISC complex
Homologues: Orthologues: chimpanzee ptr-mir-887 (100% identical), macaque mml-mir-887 (99% identical).
Diseases named in the same sentence as MIR887 in open-access papers:
MIR887 is named in the same sentence as 1 disease in open-access papers, as found by Europe PMC text mining. Sharing a sentence is not in itself a finding about the gene and the disease. The quoted sentences say what the papers report.
tumours (1 paper, 2024). "We identified MIR182, MIR183, MIR371, MIR373, MIR512-1, MIR512-2, MIR515-1, and MIR520e exhibiting high expression and MIR216b, MIR887, MIR9-2, and MIR9-3 exhibiting low expression in NANOG H/L tumours." (PMID 38693576, 2024).